LGALS3 (galectin 3)
Diseases named in the same sentence as LGALS3 in open-access papers (continued):
Sharing a sentence is not in itself a finding about the gene and the disease.
infection (continued). "In this way, galectin-3 binds to laminin and trypomastigotes to recruit them to the ECM thus facilitating initial infection." (PMID 23133440, 2012). "Increased LGALS3 expression in the ECM promotes the adhesion of T. cruzi to host cells and subsequent infection." (PMID 23133440, 2012). "At the early infection stages (Galectin-3 negative) the vacuolar membrane did not exhibit zones that were prominently perturbed." (PMID 40310862, 2025). "In an experimental infection with Cryptococcus neoformans, the absence of galectin-3 resulted in an increased bacterial load in the organs of mice and contributed to a skewed TH17 immune response in the host." (PMID 40696454, 2025). "Except for the #8 clone, galectin-3-knockdown clones significantly produced lower levels of the viral NS1 protein, which is preferentially synthesized at early times of infection, at 7 h p.i. and generated lower viral titers at 24 and 48 h compared to vector control cells." (PMID 36823664, 2023). "If the infection persists and is not controlled by neutrophils, Galectin-3 recruits macrophages to the site of infection, strengthening further defenses." (PMID 35083706, 2022). "By contrast, knockdown of LGALS3 did not impair H-1PV infection, further supporting the specificity of the interaction between H-1PV and Gal-1." (PMID 35632759, 2022). "Corresponding to this, the results of corneal fungal load (CFU) showed that on day 5 after infection, the CFU of wild type FK mice and galectin-3−/− FK mice was 45.00 ± 5.78∗104 and 90.67 ± 2.19 (P < 0.01), which mean the fungi in the galectin-3−/− model grew well and vigorously." (PMID 35437453, 2022). "Mirroring these data, galectin-3, plus LAMP-1 and actin filaments, was found around the PV containing amastigotes and trypomastigotes in murine peritoneal macrophages at early times of infection." (PMID 35046919, 2021). "Combined, our data indicated that amino acid deletions in p6Gag reduced galectin-3-mediated promotion on CRF07_BC budding, which may correlate with lower viral load and slow progression observed in clinical HIV-1 CRF07_BC infection." (PMID 32326345, 2020). "Accordingly, we suggest that the CRD of galectin-3 monomers interact with HIV-1 gp120 or CD4 molecules, triggering galectin-3 oligomers formation to further enhance their binding capabilities to CD4 or gp120, respectively, thus facilitating HIV-1 CRF07_BC infection." (PMID 32485969, 2020). "Galectin-3 has been shown to limit infections by the gram-negative bacteria Helicobacter pylori, but also limits infection by gram-positive Streptococcus pneumoniae partly by increasing neutrophil phagocytosis of the bacteria." (PMID 31781126, 2019). "Therefore, similar to what was observed during the initial activation of naive CD8+ T cells after MHV68 infection, the stimulation of specific memory CD8+ T cells exhibited galectin-3 recruitment at the immune synapse." (PMID 30388704, 2018). "In addition, the LC3 recruitment to damaged endosomes containing GAS (Galectin-3-poisitve GAS) was suppressed in Beclin 1 KO cells at 2 and 4 h post-infection in comparison with that of wild-type cells." (PMID 28085926, 2017). "First, galectin-3 may modulate EV71 assembly, since the intracellular viral loads were not significantly different between RD and G3KO cells until 24 h of infection." (PMID 28002441, 2016). "Galectin-3−/− mice have been shown to be highly resistant to infection with another Gram negative bacterium Salmonella with KO mice exhibiting lower bacterial burdens." (PMID 23527230, 2013). "We studied the balance of Th1/Th2 responses to P. brasiliensis experimental infection in the absence of galectin-3." (PMID 19229338, 2009). "The T. gondii model has shown that galectin-3 leads to reduced organ inflammation and Th1-polarized immune response, which does not alter mice survival to the infection." (PMID 19229338, 2009).
infection (continued). "After 6 h post-infection, galectin-3, but not the lysosomal membrane proteins (LAMP)-2, was found to be accumulated around T. cruzi amastigotes, supporting the notion that this lectin encloses the parasite that has recently lysed the phagolysosome and escaped to the cytoplasm." (PMID 35046919, 2021). "However, immunofluorescence assays carried out after 96 h post-infection showed a diminished number of parasites in cells in the absence of galectin-3, which did not interfere with T. cruzi escape from PV into the cytoplasm." (PMID 35046919, 2021). "Taken together, these data suggest that galectin-3 plays an important role in enhancing immune cell migration from the pulmonary vasculature to the site of infection within the pulmonary airspaces that is independent of bone marrow granulopoiesis, and pulmonary chemokine production." (PMID 32750085, 2020). "Also, 4 weeks after infection, significantly higher percentage of activated, CD86 positive, CD11c+, CD11c+CD11b+, and CD11c+CD1d+ dendritic cells was detected in the livers of WT compared with Lgals3−/− mice." (PMID 31231399, 2019). "Interestingly, infected Lgals3–/– mice showed a drop in serum levels of Th1 and Th2 cytokines, including IFN-γ, IL-2, IL-5, IL-6, IL-10, and TNF, compared with WT mice; these differences were significantly pronounced at 14 days but ceased at 28 days post-infection." (PMID 35046919, 2021). "Interestingly, in recent years, it has been discovered that Helicobacter pylori, a common Gram-negative bacillus, whose infection can upregulate the galectin-3 expression in gastric epithelium, damages the blood-brain barrier and causes central system diseases." (PMID 34900086, 2021). "However, in galectin-8−/− macrophages, but not in galectin-3−/− or galectin-9−/− macrophages, Mtb was not controlled at 24 h postinfection, and bacterial burdens were significantly higher throughout the course of infection." (PMID 34225486, 2021). "Interestingly, no increase of AST and ALT after infection was observed in serum of Lgals3−/− mice." (PMID 31231399, 2019). "By contrast, mice lacking the gene for galectin-3, Lgals3−/−, survived both CEP and CEP Δpigj infections." (PMID 39302131, 2024).
cardiovascular diseases (110 papers, 2012 to 2026). "Galectin-3 levels are significantly associated with adverse outcomes across various cardiovascular disorders, notably HFpEF." (PMID 39063659, 2024). "Understanding galectin-3’s multifaceted involvement in cardiovascular diseases is crucial for unlocking its therapeutic and diagnostic potential in managing conditions like diastolic dysfunction." (PMID 39063659, 2024). "Given the limited treatment options for diastolic dysfunction and galectin-3’s importance in cardiovascular diseases, investigating its role offers promise for enhancing risk assessment and guiding therapeutic strategies." (PMID 39063659, 2024). "Overall, these clinical studies underscore the significance of galectin-3 in the pathogenesis and prognostication of diastolic dysfunction, highlighting its potential as a therapeutic target and diagnostic tool in cardiovascular disease management." (PMID 39063659, 2024). "Observational studies evaluating the association of serum galectin-3 with mortality, cardiovascular disease and arterial stiffness in hemodialysis patients were included." (PMID 38519721, 2024). "Galectin-3 has been proposed to be implicated in various pathways in the pathophysiology of cardiovascular diseases." (PMID 38519721, 2024). "The aim of this study was to assess the association between fibrinogen (FIB), interleukin-6 (IL-6), C-reactive protein (CRP) and galectin-3 (Gal-3) and the risk of cardiovascular disease using meta-analysis." (PMID 37485268, 2023). "A random-effects model was used to combine inflammation factor-associated outcomes and cardiovascular disease outcomes, except in the case of galectin-3, where a fixed-effects model was used because of less heterogeneity." (PMID 37485268, 2023). "We provided evidence for the utility of BNP, hsTroponin-I, and Galectin-3 in the prediction of future HFpEF in asymptomatic event-free populations with cardiovascular disease risk factors." (PMID 33563287, 2021). "In women, higher serum galectin-3 concentrations were observed compared to men, as well as a stronger correlation between concentration of serum galectin-3 and other cardiovascular disease risk factors." (PMID 35053194, 2021). "Galectin-3 is a carbohydrate-binding lectin implicated in the pathophysiology of cardiovascular diseases and highly expressed within atherosclerotic lesions of mice and humans." (PMID 32967121, 2020). "Low sTWEAK levels and high galectin-3 levels have previously been linked to the development of cardiovascular disease and increased mortality." (PMID 33261587, 2020). "Galectin-3 levels have been shown to correlate with clinical outcomes in patients with atherothrombosis, and to correlate with traditional risk factors for cardiovascular diseases and with mortality in subjects from the general population." (PMID 29327139, 2018). "Elevated galectin-3 levels are linked to various cardiovascular disorders." (PMID 40149705, 2025). "Arginine and its metabolites, asymmetric dimethylarginine, symmetric dimethylarginine, and galectin 3, may be important biomarkers of cardiovascular diseases risk." (PMID 40638465, 2025). "The use of GDF-15, soluble ST2, and galectin-3 as diagnostic tools presents a promising strategy for the early detection of diseases, categorizing risk, and enhancing patient outcomes in various medical conditions, including cardiovascular diseases." (PMID 39328401, 2024). "Integrating galectin-3 measurements into clinical practice may refine diagnostic accuracy and facilitate tailored management strategies for cardiovascular diseases." (PMID 39063659, 2024). "Taken together, the current research evidence suggests that high levels of fibrinogen, interleukin-6, C-reactive protein and galectin-3 are risk factors for cardiovascular disease and can be used as biomarkers to predict the development of cardiovascular disease to some extent." (PMID 37485268, 2023).
cardiovascular diseases (continued). "Besides its role in a variety of other cardiovascular disorders, galectin-3 plays a crucial role in the progression of AF-associated atrial remodeling, which itself perpetuates AF." (PMID 38069127, 2023). "All these studies indicate that galectin-3 plays a key pathogenic role in cardiovascular diseases." (PMID 37513890, 2023). "Previous investigations on the association between galectin-3 and cardiovascular disease indicated that galectin-3 concentrations in circulation might be a potential biomarker for cardiovascular disease." (PMID 36175599, 2022). "This study aimed to investigate the linkage between serum markers of obesity and risk of cardiovascular diseases, with particular reference to the adipokines galectin-3, plasminogen activator inhibitor-1 (PAI-1), IL-1β, CRP, monocyte chemoattractant protein-1 (MCP-1), and insulin." (PMID 32290863, 2020). "This study aimed to investigate the linkage between adipocytokines and insulin with the cardiovascular disease risk, with particular reference to the adipokines galectin-3, plasminogen activator inhibitor-1, and interleukin-1-beta, C-reactive protein, and monocyte chemoattractant protein." (PMID 32290863, 2020). "Several confounding factors linked to inflammation and fibrosis in other organs, such as female sex, age or renal function, mostly influence Galectin-3 levels; impaired renal function is common in patients with cardiovascular disease, which may underlie the prognostic value of Galectin-3 in CHF." (PMID 37109323, 2023). "However, the association between galectin-3 and cardiovascular diseases in CKD patients is unclear." (PMID 33195327, 2020). "Galectin-3 is increasingly recognized as a pivotal mediator in the pathophysiology of cardiovascular diseases, particularly through its involvement in inflammation, fibrosis, and myocardial remodeling." (PMID 40699731, 2025). "The study found that elevated level of LGALS3 can be observed in almost all cardiovascular diseases and plays an important role in clinical prognosis." (PMID 39823512, 2025). "Previous studies have highlighted the importance of galectin-3 as a biomarker in assessing the severity of cardiovascular diseases." (PMID 39451549, 2024). "Galectin-3, a β-galactoside-binding lectin, has garnered attention as a potential biomarker and mediator of fibrosis and inflammation in cardiovascular diseases." (PMID 39063659, 2024). "Investigations into galectin-3’s mechanisms offer novel therapeutic avenues, including inhibitors, for cardiovascular diseases." (PMID 39063659, 2024). "Furthermore, serum galectin-3 should be assessed in conjunction with both traditional risk factors and novel biomarkers, aiming to construct combined models that would enable effective stratification of hemodialysis patients in regards to cardiovascular disease and mortality risk." (PMID 38519721, 2024). "A 10-year cohort study comprising 7968 Caucasiansindicated that higher galectin-3 levels were connected to cardiovascular disease." (PMID 39076571, 2024). "Galectin-3 also has potential in cardiovascular diseases as its levels can predict the severity of coronary slow flow phenomenon in conjunction with GDF-15." (PMID 39328401, 2024). "Galectin-3 (Gal-3) — a β-galactoside-binding lectin — has emerged as a promising biomarker in various cardiovascular disorders due to its involvement in inflammation, fibrosis, and vascular remodeling." (PMID 38239874, 2023). "One interesting biomarker in this context is galectin-3, which has been widely studied in cardiovascular diseases." (PMID 38069127, 2023). "In contrast, Galectin-3 as marker for cardiovascular disease, showed highest values at inpatient release." (PMID 37256146, 2023). "Among a large number of different biomarkers examined for the assessment of cardiovascular diseases, galectin-3 has occupied a special place in the research area due to its role in the processes of inflammation and fibrosis." (PMID 35208606, 2022).
cardiovascular diseases (continued). "These prospective studies concerning galectin-3 as a cardiac biomarker present analyses performed in cohorts composed of healthy children and children with cardiovascular diseases." (PMID 35410028, 2022). "As the first studies of galectin-3 in children with cardiovascular diseases are very optimistic, there is need for further research." (PMID 35410028, 2022). "In terms of the important roles of BaPWV and galectin-3 in cardiovascular diseases, we observed them in CAG patients." (PMID 35685493, 2022). "Galectin-3, which plays a critical role in the progression of various cardiovascular diseases, is unique since it is the only member of the galectin family with an extended N-terminal domain." (PMID 35191812, 2022). "Galectin-3 not only serves as a biomarker, but is also a contributor to cardiovascular disease and mortality." (PMID 34045984, 2021). "Galectin-3 can be not only a clinically important biomarker of fibrotic process in car-diovascular diseases, but also an interesting therapeutic target that can possibly decelerate the progression of heart fibrosis." (PMID 35053194, 2021). "In summary, it should be stressed that the proinflammatory effect of galectin-3 is not only limited to its participation in the pathogenesis of cardiovascular diseases." (PMID 35053194, 2021). "Consequently MMP12 cleavage may underlie the increased circulating levels of galectin-3 observed in patients with cardiovascular diseases, particularly given that commercially available ELISAs for galectin-3 do not discriminate between full-length and cleaved forms of galectin-3." (PMID 32295421, 2020). "Galectin-3, a member of the β-galactoside-binding lectin family, has emerged as a new prognostic biomarker for a series of cardiovascular diseases, such as congestive heart failure and coronary artery disease." (PMID 33195327, 2020). "Although the evidence is conflicting, PWV and galectin-3 are still considered new predictors of cardiovascular diseases." (PMID 33195327, 2020). "The Galectin 3 values of our patients are in line with values reported in other studies conducted on patients with cardiovascular disease and are higher than those detected in healthy individuals." (PMID 31035456, 2019). "Plasma galectin‐3 (Gal‐3) is elevated inside and drives diverse systemic inflammatory disorders, including cardiovascular diseases." (PMID 30536538, 2019). "In the last few years, several studies have focused their attention on the role of galectin-3 in cardiovascular disease, especially as a reliable biomarker of ECM turnover in HF patients that correlated with the adverse outcome in HF." (PMID 26116131, 2014). "Galectin-3 is a β-galactoside-binding lectin involved in inflammatory responses, fibrosis, and tissue remodeling, and has been investigated as a potential biomarker in cardiovascular diseases." (PMID 42194674, 2026). "Gal-3, also known as galectin-3, a lectin that binds β-galactosides, has gained attention as a novel biomarker and pathophysiological mediator in cardiovascular disease, where it contributes to inflammation, fibrosis, metabolic dysregulation and cardiac remodeling." (PMID 40699731, 2025). "Of the biomarkers under study, growth/differentiation factor-15 (GDF-15), Galectin-3 (Gal-3), and soluble suppression of tumorigenicity 2 (sST-2) stand out as potential key markers for cardiovascular disease (CVD) and its outcomes, possibly offering insights into the cardiac structure." (PMID 38672149, 2024). "Galectin-3 plays a central role in different types of cardiovascular diseases." (PMID 37513890, 2023). "Since the processes of inflammation and fibrosis play an important role in the pathogenesis of many cardiovascular diseases, galectin-3 has encouraged researchers in the field of cardiology to conduct various studies on the impact of this biomarker on cardiovascular pathology." (PMID 35208606, 2022).